BDNF (brain derived neurotrophic factor)
Diseases named in the same sentence as BDNF in open-access papers (continued):
Sharing a sentence is not in itself a finding about the gene and the disease.
psoriasis (12 papers, 2013 to 2025). An autoimmune condition characterized by red, well-delineated plaques with silvery scales that are usually on the extensor surfaces and scalp. "Further studies shoulddetermine if BDNF is increased after specific psoriasis treatments, and associatedwith different disease stages." (PMID 26200230, 2015). "Previous studies have described reduced plasma levels of BDNF in psoriatic patients, with similar levels in both mild and severe cases of psoriasis." (PMID 39457071, 2024). "In pre-clinical studies on mice with psoriasis, the abnormal modification of mRNA levels of the brain-derived neurotrophic factor (BDNF) and tropomyosin receptor kinase B (TrkB) was found in the mouse brains." (PMID 36676137, 2023). "We review existing studies examining the role of psychological or psychosocial stress at the molecular level in AD and psoriasis, highlighting the role of the HPA axis and IL-18 in AD, CRH and BDNF in psoriasis, and cortisol levels in both." (PMID 35572606, 2022). "Regarding psoriasis, BDNF was found to be crucial in the maintenance of normal keratinocyte apoptosis and epidermal homeostasis, while p75NTR protein was found to be absent in lesional psoriasis skin." (PMID 34685457, 2021). "Our finding, that BDNF is decreased in psoriasis,supports the concept of a brain-skin connection in psoriasis." (PMID 26200230, 2015). "Interestingly, in skin diseases such as vitiligo, psoriasis or acne vulgaris the level of BDNF is significantly lower compared to the control group." (PMID 36362520, 2022). "Thus,we aimed to determine if BDNF plasma levels are decreased in psoriasis patients comparedwith controls." (PMID 26200230, 2015). "Similar BDNF levels were found in both mildand severe cases of psoriasis." (PMID 26200230, 2015). "Brain-derived neurotrophic factor (BDNF) is associated with neuroplasticity andsynaptic strength, and is decreased in conditions associated with chronic stress.Nevertheless, BDNF has not yet been investigated in psoriasis, a chronic inflammatorysystemic disease that is exacerbated by stress." (PMID 26200230, 2015).
allergic disease (11 papers, 2012 to 2025). An immune response that occurs following re-exposure to an innocuous antigen, and that requires the presence of existing antibodies against that antigen. "In contrast, some reports have suggested an important contribution of BDNF variations in the predisposition and progression of allergic diseases." (PMID 33114368, 2020). "In summary, differing expression levels of BDNF in serum and local fluids of patients with AD and symptom-free subjects indicate that BDNF plays an important role in allergic diseases." (PMID 37047077, 2023). "Mouse studies have shown augmented expression of BDNF at both the protein and mRNA levels in response to allergic reactions." (PMID 34771682, 2021). "Apart from the extensive studies of NGF and BDNF in allergic rhinitis and atopic dermatitis, the reports regarding the other genes related to neurogenic inflammation in allergies are limited and focused mainly on adult populations of patients." (PMID 32596360, 2020). "Indeed, IL-10 release by immune cells, which is enhanced by both NGF and BDNF in normal conditions, is dramatically reduced in cases of allergy." (PMID 24223945, 2013). "Following this line of reasoning, allergy-induced M2A polarization, with its increased production of IGF1, BDNF and further growth factors, would contribute to ASD via inhibition of normal pruning of synapses." (PMID 29232822, 2017). "However, we can not prove whether the effect of BDNF on NPs is disrupted by allergic diseases in this case." (PMID 38827877, 2024). "Increased expression of neurotrophin-3 and neurotrophin-4 was previously reported in allergies by several papers, although they were not studied as extensively as NGF or BDNF." (PMID 32596360, 2020).
deafness (11 papers, 2015 to 2025). An inherited or acquired condition characterized by the complete loss of the ability to hear from one or both ears. "Our findings that MMP-9 and BDNF plasma levels play an important role in governing auditory development following deafness treatment are necessarily tentative and require verification." (PMID 36835126, 2023). "Out of the tested genetic variants of MMP9 and BDNF, only rs3918242MMP9 showed significant association withauditory development in the subgroup with DFNB1-related deafness." (PMID 35061219, 2022). "After 6 weeks of deafness with neurotrophic treatment, survival of both SGCs and their PPs was generally substantially higher (BDNF, NT-3, and Cocktail, respectively) than the PBS control group." (PMID 36226314, 2022). "Numerous studies have demonstrated that exogenous BDNF delivered directly to the cochlea can protect cochlear neurons and promote neuronal survival after deafness." (PMID 35269763, 2022). "On this basis, here we also investigated the duration of deafness after kanamycin administration and compared the number of surviving cells in the organ of Corti of six (BDNF-GS study) and 14 weeks (BDNF-OP study) deaf guinea pigs." (PMID 35053747, 2021). "In the present study we have evaluated the efficacy of BDNF-loaded SPs to protect SGNs from deafness-induced degeneration and assessed the biocompatibility of the SP carrier system by quantifying the tissue response following chronic implantation." (PMID 27788219, 2016). "Consequently, there has been great interest in recent years in exploring potential therapies based on BDNF to ameliorate the degeneration of the cochlear ganglion neurons after deafness." (PMID 35269763, 2022). "Previous studies assessed the survival of spiral ganglion cells after a period up to six weeks following deafness before treatment with BDNF plus fibroblast growth factor 1 (FGF1) or before combined treatment with GDNF and ES or BDNF and ES." (PMID 32824176, 2020). "This mode of BDNF action must be taken into account in view of attempts to treat deafness by BDNF, which are not always successful." (PMID 25751404, 2015). "In their study, the authors did not report deafness etiology or duration, and the authors did not clearly indicate whether their ELISA kit differentiated pro-BDNF from BDNF, so for these reasons their results cannot be directly compared to ours." (PMID 36835126, 2023).
head and neck squamous cell carcinoma (11 papers, 2012 to 2022). A squamous cell carcinoma that arises from any of the following anatomic sites: lip and oral cavity, nasal cavity, paranasal sinuses, pharynx, larynx, and salivary glands. "In this investigation, we explored the role of cancer-associated fibroblasts (CAFs) in the regulation of the tumor microenvironment in head and neck squamous cell carcinoma (HNSCC) though a complex intercellular BDNF-TrkB signaling system." (PMID 28966935, 2017). "In contrast, this article addresses more the function of the BDNF/TrkB axis directly in the tumor cells of the head and neck squamous cell carcinoma (HNSCC)." (PMID 30641914, 2019). "We hypothesized that in head and neck squamous cell carcinoma (HNSCC), the neurotrophin brain-derived neurotrophic factor (BDNF) and its high affinity receptor TrkB regulate tumor cell survival, invasion, and therapy resistance." (PMID 30641914, 2019). "Previous studies have demonstrated a key role for BDNF-TrkB signaling in modulating the response to cytotoxic agents, and modulation of TrkB expression enhanced the sensitivity of cells to cis-Diamminedichloroplatinum Cisplatin (CDDP) in head and neck squamous cell carcinoma." (PMID 23936232, 2013).
Headache (11 papers, 2012 to 2025). Cephalgia, or pain sensed in various parts of the head, not confined to the area of distribution of any nerve. "Among patients aged 18–64, chronic pain (OR = 1.6, 95% CI 1.05–1.28, p = ***) was the leading risk factor most strongly associated with PCS in addition to headache (OR = 1.36, 95% CI 1.03–1.80, p = *) and BDNF (Val66Met; OR = 1.30, 95% CI 1.00–1.69, p = *)." (PMID 39628897, 2024). "Another study found that children with headaches had lower total cholesterol levels and higher levels of brain-derived neurotrophic factor (BDNF) compared to the control group." (PMID 41532064, 2025). "By increasing the pain threshold and improving cortical inhibitory function, exercise contributes to a reduction in the frequency and intensity of headache episodes, as it regulates brain-derived neurotrophic factor (BDNF)." (PMID 40648636, 2025). "It was also the most relatively important factor for PCS based on dominance analysis, followed by headache, being a female at birth, and BDNF (Val66Met)." (PMID 39628897, 2024). "In patients aged 18–64, the most significant difference between PCS and TBI was noted in the prevalence of headache (78.4% vs. 53.3%) followed by dizziness and giddiness (60.1% vs. 35.7%) and BDNF (Val66Met; 59.8% vs. 37.6%)." (PMID 39628897, 2024). "On the other hand, the risk factors associated with unfavorable TBI outcomes indicated by PCS in the younger patients are chronic pain, headache, and BDNF (Val66Met) SNP." (PMID 39628897, 2024). "During headache, the incoming information from the meninges releases BDNF through the center to initiate the injurious sensory system of the dura." (PMID 37090989, 2023). "During a headache, the afferent input from the meninges primes the dural nociceptive system using the central release of BDNF." (PMID 35382731, 2022). "Our preliminary data demonstrated higher levels of BDNF in children with headaches than in the controls." (PMID 33020432, 2020). "This investigation also showed that BDNF level was higher in mothers with headaches or with loss of smell/taste than in mothers without the respective symptom." (PMID 33917718, 2021). "We were not able to find any study in the literature assessing the correlation between headache frequency and levels of in vivo PGE2 and VEGF, and we found only two studies that evaluated the correlation between CSF levels (not serum) of NGF and BDNF and number of headache days." (PMID 34991456, 2022).
hypoxic-ischemic encephalopathy (11 papers, 2021 to 2025). "Additionally, a deficiency in BDNF has been identified as a significant factor in perinatal depression." (PMID 38321436, 2024). "Emerging research supports a link between BDNF levels and clinical improvement in perinatal depression." (PMID 41440970, 2025). "An elegant experimental study observed that BDNF activates autophagy by inhibiting the mTOR pathway in rats with hypoxic-ischemic encephalopathy." (PMID 38006577, 2024). "The possibility to identify specific treatments to ameliorate the effects of dysregulated maternal BDNF should be investigated in future longitudinal studies, as a potential avenue for treating perinatal depression." (PMID 34989854, 2022). "BDNF reduces the apoptosis of neurons submitted to oxygen–glucose deprivation/reoxygenation and promotes neuronal survival after neonatal hypoxic-ischemic encephalopathy." (PMID 36163004, 2022). "In pregnancy, BDNF has been mainly studied in the context of perinatal depression." (PMID 39698038, 2024). "We aimed to investigate whether BDNF may be a marker of paternal as well as maternal perinatal depression." (PMID 34989854, 2022). "After G9a overexpression in vitro and in vivo, the enrichment levels of H3K9me2 in the promoter region of BDNF were augmented, whereas the levels of BDNF were decreased, along with damaged neurons and impaired learning and memory abilities of rats with hypoxic-ischemic encephalopathy." (PMID 35439934, 2022). "Although perinatal depression has historically been underrepresented in biomarker research, emerging evidence suggests that certain markers, such as BDNF, neuroactive steroids, neuroimaging findings, and inflammatory markers, may hold translational relevance in this unique population." (PMID 41440970, 2025). "One study (N = 86) demonstrated that pregnant patients with perinatal depression treated with SSRIs had higher BDNF than those not treated with SSRIs." (PMID 41440970, 2025). "A meta-analysis reported lower BDNF serum levels in maternal perinatal depression, which is partly consistent with our finding of a significant negative correlation between depressive symptoms and BDNF protein levels in mothers." (PMID 34989854, 2022). "It has been suggested that the neurotrophin BDNF may play a role in maternal perinatal depression; however, there is currently no data regarding paternal perinatal depression." (PMID 34989854, 2022). "BDNF protein levels have previously been studied in maternal but not paternal perinatal depression." (PMID 34989854, 2022). "Researchers found that MCPS promoted long-term learning and memory in perinatal asphyxia (PA) pups by decreasing oxidative damage and acetylcholinesterase (AChE) activity in the brain, and increasing the expression of p-CREB and brain-derived neurotrophic factor (BDNF) in the hippocampus." (PMID 34504861, 2021). "The data suggest that BDNF may play a role in maternal perinatal depression, but not paternal." (PMID 34989854, 2022).
learning disorders (11 papers, 2009 to 2025). "Studies have found that anesthesia/surgery can inhibit the BDNF/TrkB signaling pathway and cause learning disorders." (PMID 40919224, 2025). "In conclusion, AGO administration significantly improves memory and learning disabilities associated with LPS administration by modulating the ERK/SorLA/BDNF/TrkB signaling pathway parallel to its capacity to adjust the autophagic process." (PMID 37712973, 2024). "The high frequency of Val66Met polymorphism among children with LD introduces the BDNF gene as a genetic modifier of learning performance in some children who manifest specific learning disorder (developmental dyslexia)." (PMID 36550387, 2023). "The Val66Met polymorphism of the BDNF gene could be proposed as a genetic modifier of learning performance in some children who manifest specific learning disorder with impairment in reading or developmental dyslexia." (PMID 36550387, 2023). "In vitro and in vivo experiments show that BDNF has neuroprotective effects against the cytotoxic effects of beta-amyloid plaques and Aβ-induced learning disabilities." (PMID 36016853, 2022). "It normalizes the levels of BDNF and associated synapsin I and CREB, reduces oxidative damage, and counteracts learning disability." (PMID 36499295, 2022). "There are also correlations between learning disabilities and increased DNA methylation and repressive histone modifications at the BDNF promoter in mice exposed to MeHg in utero." (PMID 29261810, 2017). "BDNF levels have been found to be low in children with learning disorder (LD)." (PMID 36550387, 2023). "Our former researches indicated that the dysregulation of the HPA axis reduced the levels of the second messenger cyclic nucleotides (cGMP and cAMP), subsequently decreasing the phosphorylation of CREB and BDNF expression, which, in turn, worsens memory and learning disorders." (PMID 31632240, 2019). "Further studies will be required to understand the role of BDNF in either learning disorder." (PMID 19860886, 2009). "Although the BDNF gene Val66Met polymorphism was a commonly studied gene variant within the field of cognitive neuroscience, it has not been studied in children with specific learning disorder before." (PMID 36550387, 2023). "High level of BDNF was reported in children with ADHD, and reduced in children with learning disorders." (PMID 38652370, 2024). "BDNF has been reported to be altered in ADHD and learning disorders." (PMID 38652370, 2024).
non-small cell lung carcinoma (11 papers, 2016 to 2025). A group of at least three distinct histological types of lung cancer, including non-small cell squamous cell carcinoma, adenocarcinoma, and large cell carcinoma. "It has been reported that the expression of TrkB and BDNF was associated with poor prognosis in non-small cell lung cancer and TrkB/BDNF signaling pathway could be a therapeutic target for pulmonary large cell neuroendocrine carcinoma." (PMID 26926340, 2016). "As highlighted, NCI-H322 cells are a non-small cell lung cancer cell line from a male donor, and BDNF–TrkB signaling is reported to be involved in the progression of non-small-cell lung cancer." (PMID 40626045, 2025). "In non-small cell lung cancer, miR-496 targeted BDNF-mediated PI3K/Akt signaling pathway suppresses tumorigenesis." (PMID 36518809, 2022). "The BDNF/TrkB signaling pathway seems to have functions with tumor progression, such as peritoneal carcinomatosis, bladder cancer, and non-small cell lung cancer." (PMID 28212323, 2017). "Most non-small cell lung cancer (NSCLC) cells overexpress VEGFA, and brain-derived neurotrophic factor (BDNF) enhances VEGF-dependent angiogenesis." (PMID 35805939, 2022). "In this study, we found increased MMP9 levels in the media of two non-small cell lung cancer (NSCLC) cell lines, A549 and H1299, treated with BDNF, nicotine, or epinephrine that were decreased upon cell treatment with the β-adrenergic receptor blocker propranolol." (PMID 37760996, 2023). "Similarly in non-small cell lung cancer, STAT3 and BDNF signalling have been shown to cooperatively activate proliferative signalling." (PMID 29339786, 2018).
cerebrovascular disease (10 papers, 2016 to 2025). "In patients and animal models with cerebrovascular disease, the BDNF levels are reduced in the hippocampus and blood, resulting in cognition decline." (PMID 33920851, 2021). "Also, BDNF was positively correlated with the volume of the infarction, so it is involved in the pathophysiology of cerebrovascular disease in SCD." (PMID 36774398, 2023). "Like these bioactive mediators, the platelet release of BDNF could therefore be beneficial in the healing of vascular and nerve damage in cerebrovascular disease." (PMID 34557534, 2021). "The results revealed that the combined transplantation of MSCs and EPCs achieved an improvement in cardiac function in cardiac diseases, in ALP activity and bone volume in damaged bone tissue, and in cerebral function in cerebrovascular diseases by increasing BDNF and reducing neurologic impairment." (PMID 27724974, 2016).